TBL1XR1 (TBL1X/Y related 1)
Diseases named in the same sentence as TBL1XR1 in open-access papers (continued):
Sharing a sentence is not in itself a finding about the gene and the disease.
West syndrome (3 papers, 2016 to 2023). "We reviewed the clinical features of the limited examples of West syndrome being driven by the TBL1XR1 variant." (PMID 35611576, 2022). "In this study, we collected data regarding the phenotypic and genetic variants and reviewed all reported West syndrome cases caused by TBL1XR1." (PMID 35611576, 2022). "Our results expand the pathogenic variant spectrum of TBL1XR1 and strengthen the pathogenic evidence of TBL1XR1 in West syndrome." (PMID 35611576, 2022). "In this patient, we describe a de novo TBL1XR1 variant that may lead to West syndrome via the Wnt signaling pathway." (PMID 35611576, 2022). "Our report strengthens the etiology of TBL1XR1 as a West syndrome pathogenic gene." (PMID 35611576, 2022). "There was clinical heterogeneity among all patients with TBL1XR1‐related West syndrome." (PMID 35611576, 2022). "However, the evidence relating TBL1XR1 to West syndrome is still quite limited." (PMID 35611576, 2022). "Moreover, a 5‐year‐old Japanese girl with West syndrome features was identified to have a de novo heterozygous c.209G‐A transition (c.209G‐A, NM_024665.4) in the TBL1XR1 gene, which results in a gly70‐to‐asp (G70D) substitution at a conserved residue in an F‐box‐like domain." (PMID 35611576, 2022).
Anxiety (2 papers, 2021 to 2025). Intense feelings of nervousness, tension, or panic often arise in response to interpersonal stresses. "Notably, mutant mice did not display significant differences in the time spent in the open arms, confirming that the loss of Tbl1xr1 is not impacting on anxiety, at least in this model." (PMID 33708771, 2021).
bladder cancer (2 papers, 2014 to 2015). "In addition to rediscovering previously known recurrent kinase fusions, we identified new fusion partners for many genes (for example, TPM1–ALK in bladder cancer, TBL1XR1–RET in thyroid cancer, and so on)." (PMID 25204415, 2014).
diabetes (2 papers, 2015 to 2026). "We identify the transcriptional co-factors transducin β-like 1 x-linked (TBL1X) and its homolog TBL1X-related (TBL1XR1, together TBL/R1) as crucial regulators of β-cell identity and determinants of diabetes development and progression." (PMID 42020373, 2026).
gastric tumor (2 papers, 2016 to 2022). "Analysis of GSE2701 showed that the mRNA levels of TBL1XR1 were significantly elevated in primary gastric tumor and lymph node tissues than normal gastric tissues (P < 0.05)." (PMID 27672238, 2016).
lymph node metastasis (2 papers, 2016 to 2024). "TBL1XR1 was associated with clinical stage, lymph node metastasis, number of lymph node and poor prognosis." (PMID 38347836, 2024). "TBL1XR1 was significantly higher in primary GC and lymph node metastasis lesions than normal gastric tissues, respectively (P < 0.05)." (PMID 27672238, 2016). "TBL1XR1 overexpression was significantly correlated with lymph node metastasis (P = 0.000) and advanced TNM stage (P = 0.001)." (PMID 27672238, 2016). "We found that TBL1XR1 was overexpressed in GC tissues in both mRNA and protein level and correlated with present lymph node metastasis and advanced TNM stage." (PMID 27672238, 2016). "The expression of TBL1XR1 protein and other clinicopathological features that were significant by univariate analysis (histological type, TNM stage, and lymph node metastasis status) were included in the multivariate analysis." (PMID 27672238, 2016). "It was showed that TBL1XR1 protein overexpression was significantly related with advanced TNM stage (P = 0.001) and present lymph node metastasis (P = 0.000)." (PMID 27672238, 2016). "TBL1XR1 expression was related with FIGO stage, lymph node metastasis and overall survival." (PMID 38347836, 2024). "In addition, we demonstrated that TBL1XR1 protein expression was significantly related with lymph node metastasis, advanced tumor stage, and poor prognosis but was not with gender, age at surgery, tumor size, and histological type." (PMID 27672238, 2016).
ovarian carcinoma (2 papers, 2024). A malignant neoplasm originating from the surface ovarian epithelium. "TBL1XR1 silencing in ovarian cancer cells decreased VEGF-C expression and a strong association between VEGF-C and TBL1XR1 was revealed in ovarian cancer tissues." (PMID 38347836, 2024). "Additionally, increased TBL1XR1 levels were linked with a poor prognosis for ovarian cancer patients." (PMID 38347836, 2024). "In general, TBL1XR1 might serve as a new target for treatment and a diagnostic tool for ovarian cancer." (PMID 38347836, 2024). "According to reports, TBL1XR1 inhibited transcriptional activation controlled by ER in breast and ovarian cancer cell lines by acting as an ER corepressor." (PMID 38347836, 2024). "In breast and ovarian cancer, TBL1XR1 was primarily found in the nucleus and in small amounts in the cytoplasm." (PMID 38347836, 2024).
pancreatic ductal adenocarcinoma (2 papers, 2022 to 2024). An infiltrating adenocarcinoma that arises from the epithelial cells of the pancreas. "Patients with low TBL1XR1 expression exhibited a more prolonged overall time than those with high TBL1XR1 expression in pancreatic ductal adenocarcinoma (PDAC), and excessive expression of TBL1XR1 was linked with TNM phase." (PMID 38347836, 2024). "Additionally, it is known that TBL1XR1 knockdown refers to a strong suppressor for proliferation and anti-apoptosis activities of pancreatic ductal adenocarcinoma cells." (PMID 35475502, 2022).
thyroid cancer (2 papers, 2014 to 2021). "Besides the present work, TBL1XR1/RET was previously found in one patient from The Cancer Genome Atlas (TCGA) thyroid cancer series." (PMID 34282777, 2021).
acute myeloid leukemia (1 paper, 2024). Acute myeloid leukemia (AML) is a group of neoplasms arising from precursor cells committed to the myeloid cell-line differentiation. "Another report in an acute myeloid leukemia (AML) patient identified a novel fusion TBL1XR1-PDGFRB and this fusion may be sensitive to dasatinib." (PMID 38347836, 2024).
atherosclerosis (1 paper, 2026). A disease characterized by the build-up of fatty material and calcium deposition in the arterial wall resulting in partial or complete occlusion of the arterial lumen. "Restoration of TBL1X/TBL1XR1 functionality may thus serve as a novel, druggable strategy for preventing or limiting atherosclerosis progression." (PMID 41539423, 2026).
cerebral palsy (1 paper, 2024). A group of disorders affecting the development of movement and posture, often accompanied by disturbances of sensation, perception, cognition, and behavior. "As awareness of the TBL1XR1 phenotype has expanded, it has been added to a wider array of panels including those for neurodevelopmental disorders, ASD, ID, cerebral palsy, and hypotonia." (PMID 38378692, 2024).
chronic obstructive pulmonary disease (1 paper, 2022). A chronic and progressive lung disorder characterized by the loss of elasticity of the bronchial tree and the air sacs, destruction of the air sacs wall, thickening of the bronchial wall, and mucous accumulation in the bronchial tree. "TBL1XR1 is one of the chronic obstructive pulmonary disease-related genes." (PMID 35475502, 2022).
Coronary Artery Disease (1 paper, 2025). "Transducin beta‐like 1 X‐linked receptor 1 (TBL1XR1) is significantly upregulated in the peripheral blood of patients with coronary artery disease (CAD)." (PMID 41476864, 2025).
coronary atherosclerosis (1 paper, 2025). Atherosclerosis of the coronary vasculature. "Additionally, a positive correlation was observed between Gensini score and relative TBL1XR1 expression, indicating that higher TBL1XR1 levels were associated with more severe coronary atherosclerosis." (PMID 41476864, 2025). "Higher TBL1XR1 expression was correlated with increased severity of coronary atherosclerosis." (PMID 41476864, 2025). "TBL1XR1 may promote the initiation and development of coronary atherosclerosis by regulating TG metabolism via the PPAR pathway." (PMID 41476864, 2025). "Consequently, TBL1XR1 modulated TG metabolism by regulating PPARα expression, thereby contributing to the initiation and development of coronary atherosclerosis." (PMID 41476864, 2025).
esophageal cancer (1 paper, 2021). A primary or metastatic malignant neoplasm involving the esophagus. "Significantly, ZFP36 strongly reduced VEGF-C mRNA levels in TBL1XR1-overexpressing esophageal cancer cells, resulting in robust inhibition of TBL1XR1-mediated LEC migration and tube formation." (PMID 34853315, 2021).
hearing loss (1 paper, 2016). "Mutations in another subunit of the NCoR-SMRT complex, TBL1XR1, were found to cause hearing loss as well." (PMID 27603907, 2016).
lymphoplasmacytic lymphoma (1 paper, 2024). A clonal neoplasm of small B-lymphocytes, lymphoplasmacytoid cells, and plasma cells involving the bone marrow, lymph nodes, and the spleen. "The TBL1XR1 gene is frequently affected by mutations in ABC-DLBCL, and has been described in IVLBCL, as well as in MYD88-wild type lymphoplasmacytic lymphoma cases." (PMID 38441683, 2024).
metastasis (1 paper, 2017). The spread or migration of cancer cells from one part of the body (where they first appeared) to another. "Briefly, we selected 47 stage IV CRC patients with synchronous liver metastasis (CRCLM) as cohort I to investigate the possible relationship between TBL1XR1 and CRC metastasis." (PMID 28295012, 2017).
nasal polyp (1 paper, 2012). "Notably, we found that the genes involved in the Wnt pathway were enriched (P = 0.026), and four genes (FZD5, LRP6, PPP2R1B, and TBL1XR1) in this pathway switched to proximal APA sites in nasal polyp tissue." (PMID 23185289, 2012).
tumor (37 papers, 2014 to 2025). "According to past researches, TBL1XR1 is linked to tumour development, metastasis, chemoresistance, and subpar overall survival in a number of malignancies." (PMID 38607540, 2025). "TBL1XR1, a transducin β‐like 1 X‐linked receptor 1, is a tumor‐suppressor gene with E3 ubiquitin ligase activity, mediating transcriptional repression through NF‐κB and WNT signaling pathways." (PMID 34791836, 2022). "The predicted activities of motifs associated with EPAS, BCL3, FOXM1, and TBL1XR1 were higher in ILC than in the non‐ILC tumor cells." (PMID 33616307, 2021). "One tumor displayed a fusion whose 5′-end contained a portion of TBL1XR1 (transducin (beta)-like 1 X-linked receptor 1; located on chromosome 3q26.32), and the 3′-end—a portion of RET (located on chromosome 10q11.2)." (PMID 34282777, 2021). "TBL1XR1 is mutated in various tumors, promoting tumor cell survival, and has been linked to a poor prognosis." (PMID 32316399, 2020). "High expression level of TBL1XR1 was positively associated with tumor size (OR =2.56; 95 % CI, 1.51–4.35), depth of tumor (OR =2.56; 95 % CI, 1.51–4.35), lymph node metastasis (OR =3.07; 95 % CI, 1.66–5.67) and TNM stage (OR =8.48; 95 % CI, 2.25–31.97)." (PMID 28977891, 2017). "Transducin β-like 1 X-linked receptor 1 (TBL1XR1) is an important transcriptional cofactor involved in the regulation of many signaling pathways, and is associated with carcinogenesis and tumor progression." (PMID 25145705, 2014). "Furthermore, TBL1XR1 expression was also linked to c-erbB2 and Ki-67 expression levels, as well as clinical stage, tumor categorization, classification of nodes, metastasis categorization, and histological grade." (PMID 38347836, 2024). "Furthermore, increased serum alpha fetoprotein levels, more tumor emboli, advanced clinical phases, larger maximum tumor sizes, and an aggressive histological grade were all associated with TBL1XR1 upregulation in LIHC." (PMID 38347836, 2024). "In the tumor cells characterized here (A549), TBL1XR1 has a T290A missense mutation of unknown significance whose impact will require further investigation." (PMID 38443662, 2024). "The closest gene to NAALADL2 is TBL1XR1, which is implicated in tumour development and progression." (PMID 32796921, 2020). "Furthermore, elevated TBL1XR1 was associated with unfavorable clinicopathological characteristics including tumor size, depth of invasion, lymph node metastasis and TNM stage." (PMID 28977891, 2017). "However, the study from Kuang showed that there was an association between TBL1XR1 expression and tumor size, histological grade, disease stage and prognosis in HCC." (PMID 28977891, 2017). "In conclusion, from the available evidence, we found that high TBL1XR1 expression level was associated with poor clinical outcomes in cancer patients, and TBL1XR1 might be served as a valuable tumor biomarker for prognosis and clinicopathology." (PMID 28977891, 2017). "Furthermore, the clinicopathological value of TBL1XR1 was confirmed in tumor size, depth of invasion, lymph node metastasis and TNM stage, suggesting that TBL1XR1 was involved in tumor progression and its overexpression was associated with unfavorable clinicopathologic features." (PMID 28977891, 2017). "Another study found that patients with TBL1XR1 mutations in primary testicular lymphoma (PTL) had worse overall survival and were more likely to have more tumor infiltration." (PMID 38347836, 2024). "TBL1XR1 levels correlated with local tumour invasion, late tumor, lymph node, TNM stage and poor prognosis." (PMID 38347836, 2024). "Abnormal expression of TBL1XR1 in CRC cancer tissues was strongly linked with high proportions of metastases towards liver and was an independent prognostic factor for tumor recurrence." (PMID 38347836, 2024). "In PDAC cells, TBL1XR1 knockdown inhibited cell growth and colony formation in vitro and decreased tumor expansion in mice models." (PMID 38347836, 2024).
tumor (continued). "The nonsynonymous variants detected in TBL1XR1 and CCR6 were based on the high VAF considered to be present in the majority of the tumor cells." (PMID 35205758, 2022). "The nonsynonymous somatic variants detected in TBL1XR1 and PAX5 were all regarded as major clonal variants, i.e., present in the majority of tumor cells." (PMID 35205758, 2022). "In primary disease, gains/amplifications occurred in 15.99% (95% CI: 13.02–18.95) and 14.96% (95% CI: 12.08–17.84%) for NAALADL2 and TBL1XR1 respectively, increasing in frequency in higher Gleason grade and stage tumours." (PMID 32796921, 2020). "High expression of TBL1XR1 in primary tumor tissues was correlated with increasing number of liver metastases (P = 0.020)." (PMID 28295012, 2017). "According to the Kaplan-Meier survival curves and log-rank test, we identified that high expression of TBL1XR1 in either primary tumor tissues (P = 0.014) or liver metastases (P = 0.041) was correlated with poor DFS." (PMID 28295012, 2017). "Overall, 22.6% of tumours harboured a coding mutation in one of the seven Mut-driver genes involved in chromatin function (KMT2C, ARID1A, NCOR1, CTCF, KDM6A, PRBM1 and TBL1XR1)." (PMID 27161491, 2016). "Although TBL1XR1 is thought to be involved in carcinogenesis and tumor progression in multiple studies, the relationship between TBL1XR1 and GC is unclear." (PMID 27672238, 2016). "RT-PCR and real-time PCR revealed that TBL1XR1 mRNA was upregulated in tumor samples, confirming that TBL1XR1 is overexpressed in NPC patients." (PMID 25145705, 2014). "In agreement with the results above, TBL1XR1 was barely detected in normal nasopharyngeal epithelial tissues, while strong expression was observed in the tumor cells of NPC samples." (PMID 25145705, 2014). "Moreover, after cisplatin treatment, growth of xenografted tumors with TBL1XR1 knockdown was remarkably inhibited while TBL1XR1 overexpression maintained the tumor growth." (PMID 38347836, 2024). "In addition, both TBL1XR1 mRNA and protein expression in paired NSCLC tissues was measured and TBL1XR1 was significantly upregulated in tumor tissues and predicted poor prognosis in NSCLC." (PMID 38347836, 2024). "Notably, TBL1XR1 and ZEB2 mutations were enriched in ERG-deleted ALL (present in 21% and 14% of tumours, respectively)." (PMID 34753926, 2021). "Recently, many studies showed that the expression of TBL1XR1 was elevated at mRNA level or protein level in multiple human cancers and the aberrant expression of TBL1XR1 could contribute to carcinogenesis and tumor progression." (PMID 28977891, 2017). "Therefore, the tumor-promoting effect of TBL1XR1 is at least partially mediated through regulating the transcription activity of β-catenin." (PMID 28295012, 2017). "Elevated TBL1XR1 expression is correlated with lymph node metastasis and advanced tumor stage and may serve as an independent factor for poor prognosis in GC patients." (PMID 27672238, 2016). "However, tumors formed by vector control cells, or by cells with depleted endogenous TBL1XR1, exhibited a striking inhibition of tumor growth in terms of both tumor volume and weight after cisplatin treatment." (PMID 25145705, 2014). "In the current study, to elucidate whether and how TBL1XR1 is involved in the aggression and recurrence of CRC, we initially evaluated TBL1XR1 expression in primary tumor tissues and paired liver metastases from 47 stage IV patients with synchronous liver metastasis." (PMID 28295012, 2017). "Therefore, we suspect that current chemotherapy strategies may partly inhibit the TBL1XR1-regulated tumor aggression because we didn’t find clinical significance of TBL1XR1 in stage III patients." (PMID 28295012, 2017). "In addition, TBL1XR1 has been found to affect carcinogenesis and tumor progression." (PMID 25145705, 2014). "WGS of the patient tumour also detected the fusion of TP63-TBL1XR1, showing a balanced inversion of TP63 and TBL1XR1." (PMID 40715645, 2025).
tumor (continued). "Four of these genes were significantly upregulated in tumor tissues (p < 0.0001 for all comparisons): SLC27A2, TXNDC16, TBL1XR1, and GDAP1." (PMID 41373732, 2025). "TBL1XR1 was primarily restricted in the nucleus in original CRC tissues and metastases tumor of liver, exhibiting little positive staining in the cytoplasm." (PMID 38347836, 2024). "At the very beginning, TBL1XR1 was reported to be upregulated in 75.0% (21/28) of LUSC tumour tissues at mRNA level and in 53.3% (8/15) of LUSC tumor samples at protein levels." (PMID 38347836, 2024). "Among them, some transcription factors have been reported to mediate the EMT process, such as TBL1XR1, STAT6, ETV6, and SMARCA4, indicating their potential to regulate VM and promote tumor invasion." (PMID 38694917, 2024). "In previous studies, the biological significance of TBL1XR1, FKBP1A, and PPM1G in tumours has been well-documented." (PMID 38049741, 2023). "In this study, we explored the expression pattern of TBL1XR1 in CRC patients with different clinical stages (TNM I-IV), including both the primary tumor tissues and liver metastases." (PMID 28295012, 2017). "In this study, we investigated the expression of TBL1XR1 in primary CRC tissues and liver metastases from TNM stage IV CRC patients, and found that its expression in primary tumor tissues was an independent prognostic factor for tumor recurrence." (PMID 28295012, 2017). "The expression of TBL1XR1 in primary tumor tissues, but not in liver metastases, was correlated with the number of liver metastases." (PMID 28295012, 2017). "Another TF—TBL1XR1 targeting rU-pS genes was not considered for network analysis since it's mRNA and corresponding protein levels were not significantly regulated between tumor and non-tumor tissues." (PMID 33384992, 2020). "However, elevated TBL1XR1 was not significantly correlated with age, gender or tumor differentiation." (PMID 28977891, 2017). "The previously identified TFs—STAT1, STAT3, KDM1A, PML RELA, and TBL1XR1—did not exhibit a deviating correlation between the early and late tumor stages, indicating that their correlation remains constant throughout the different stages of the tumor compared to non-tumor tissues." (PMID 33384992, 2020).